EMX2 (empty spiracles homeobox 2)
Diseases named in the same sentence as EMX2 in open-access papers (continued):
Sharing a sentence is not in itself a finding about the gene and the disease.
papillary thyroid cancer (1 paper, 2018). "In this study, using data from the Cancer Genome Atlas-Thyroid Cancer (TCGA-THCA), we aimed to examine the expression profile of EMX2 and its antisense transcript EMX2OS in papillary thyroid cancer (PTC), their prognostic value and potential regulatory networks." (PMID 30576338, 2018).
sarcopenia (1 paper, 2025). Progressive decline in muscle mass due to aging which results in decreased functional capacity of muscles. "Five key CGs—NOX4, STC2, NEK6, IGSF10, and EMX2—were identified as molecular links between SSc and sarcopenia." (PMID 40977679, 2025).
schizophrenia (1 paper, 2007). A major psychotic disorder characterized by abnormalities in the perception or expression of reality. "Two novel candidate genes, PLSCR4 and EMX2, were confirmed as differentially expressed in schizophrenia between suicide completers vs. non-suicide groups." (PMID 17997842, 2007).
squamous cell carcinoma (1 paper, 2025). A carcinoma arising from squamous epithelial cells. "Although the EMX2-transfected KYSE510 cell-derived tumor showed a duct-like configuration, the origin of these cells was confirmed as squamous cell carcinoma by positive p63/CK14 immunostaining, except for the limited cells forming the ducts, possibly due to dysdifferentiation." (PMID 40564092, 2025).
thyroid cancer (1 paper, 2018). "In this study, using data from the Cancer Genome Atlas-Thyroid Cancer (TCGA-THCA), we examined the expression profile of EMX2 and EMX2OS in PTC, their prognostic value and potential regulatory networks." (PMID 30576338, 2018).
urinary tract obstruction (1 paper, 2011). Blockage of the normal flow of contents of the urinary tract. "Pax2+/−;Emx2+/− mice harbor duplex systems associated with urinary tract obstruction, bifid ureter and a high penetrance of vesicoureteral reflux." (PMID 21731775, 2011).
uterine corpus endometrial carcinoma (1 paper, 2022). A endometrial carcinoma (disease) that involves the body of uterus. "It is also a fundamental protein necessary for the development of the reproductive tract; it is therefore not surprising that it was found to be specific for uterine corpus endometrial carcinoma in the current study: EMX2 expression was noted mainly within UCEC and to a small extent within BLCA." (PMID 35361846, 2022).
viral infection (1 paper, 2024). "The N-terminal part of eMX2 is essential for capsid binding, and it appears that, upon viral infection, eMX2 is distributed around the nucleus." (PMID 39861793, 2024).
tumor (22 papers, 2012 to 2025). "In several cancers, dysregulation of EMX2 expression has been implicated in altering cellular plasticity and tumor progression." (PMID 40564092, 2025). "Although the tumor suppressor role of EMX2 might help to explain the association between EMX2/EMX2OS expression and better RFS in classical PTC, the exact regulatory effect of EMX2/EMX2OS in this variant have been not explored." (PMID 30576338, 2018). "Since EMX2 is a transcription factor implicated in the control of Teneurin gene expression, we searched for evidence of a potential association of EMX2 and the Teneurins in tumor cells." (PMID 28472127, 2017). "Analysis of clinical samples revealed variable expression of EMX2, with levels generally lower levels in tumor tissues compared to adjacent normal tissues." (PMID 40564092, 2025). "The observed downregulation of EMX2 in ESCC tissues is consistent with reports in other malignancies where EMX2 functions as a tumor suppressor gene." (PMID 40564092, 2025). "In tumors with sarcomatoid transformation, high expression of EMX1 and EMX2 reveals reverberant pathways that override the tumor suppressive role during the local progression of all tumor types." (PMID 39337467, 2024). "The results showed that there is a significant correlation between tumor EMX2 expression down-regulation and CRLM." (PMID 36348319, 2022). "The Cox proportional hazard model was used to examine the distant metastasis rate of EMX2 overexpression tumor patients and EMX2 low expression tumor patients." (PMID 36348319, 2022). "The observations regarding the co-dependence of post-ROC genes and tumor progression-related genes are generally consistent with both prognostic outcome and IHC data; however, EMX2 presented intriguing tendencies." (PMID 35361846, 2022). "The targets identified by the tumor vs tumor comparisons (EMX2, PTPRN, SCG5) required a representative cohort for ROC analysis; these three genes concern only UCEC and PAAD tumors." (PMID 35361846, 2022). "How does activation of the canonical Wnt pathway affect the tumor suppressor activity of the EMX1/EMX2 genes?" (PMID 34364391, 2021). "Located in the tissue-specific enhancer of a tumor suppressor gene EMX2, eRNA EMX2OS was lowly expressed in kidney renal clear cell carcinoma specimens and associated with poor prognosis of tumor patients." (PMID 34671565, 2021). "By restricting Emx2 overexpression (Emx2 overexpression is highly toxic to neurons) in the tumor cells in xenograft mice, the antioncogenic activity of Emx2 was evidence." (PMID 29507709, 2018). "Several studies emphasize a tumor suppressor gene function for EMX2, initially suggested by its location within a genomic region of allelic loss in uterine endometrial adenocarcinoma." (PMID 30514244, 2018). "In our patient collective, EMX2 was frequently down-regulated in tumor tissue in comparison to matched normal mucosa samples." (PMID 28830374, 2017). "Intriguingly, tumor cell migration was significantly increased upon knockdown of EMX2 in this cell line." (PMID 28830374, 2017). "In vitro knockdown of EMX2 leads to increased tumor cell migration while adenoviral restoration of EMX2 is associated with decreased migration." (PMID 28830374, 2017). "Consistent with our results obtained from CaCo2 cells, adenoviral overexpression of EMX2 resulted in significantly decreased migration of DLD1 tumor cells." (PMID 28830374, 2017). "This was found by cotransplanting conditionally engineered tumor cells, alternatively expressing Emx2 or a control transgene, into the cortical parenchyma of wild type mouse pups and scoring the outcome one week later." (PMID 27191499, 2016). "Further, we observed nuclear localization of EMX2 in those specimens and found EMX2 protein down-regulation in the tumor tissues when compared to their matched normal tissues, consistent with our previous results." (PMID 26132438, 2015).
tumor (continued). "At completion of the experiment tumor mass in Ad-EMX2 infected mice also significantly less than that in control group (P<0.05 for MKN28 tumor, P<0.01 for AGS tumor)." (PMID 23029345, 2012). "Staining intensity of a proliferative marker Ki67 of tumor specimens at completion of the experiment showed that delivery of Ad-EMX2 significantly diminished the Ki-67 staining (P<0.01), suggesting cell proliferation inhibition in tumors." (PMID 23029345, 2012). "Emerging evidence suggests that EMX2 may play a context-dependent role in tumorigenesis, acting as a tumor suppressor, depending on the tissue type and cellular environment." (PMID 40564092, 2025). "In addition, we investigated the relationship between EMX2 expression and tumor stemness by assessing its effect on colony formation in soft agar and side population (SP) cells, which are enriched for CSCs." (PMID 40564092, 2025). "EMX2 exerts tumor-suppressive functions in TNBC by directly binding to the E-cadherin promoter to maintain the epithelial phenotype and by repressing the expression of key EMT transcription factors such as TWIST1, thereby inhibiting EMT and cancer stem cell (CSC) properties." (PMID 40969325, 2025). "Taken together, EMX2 may have a unique function in cancer cells other than that of a tumor suppressor or oncogene." (PMID 40564092, 2025). "They highlighted that EMX1 and EMX2 act as tumor suppressors by restraining the effector of the canonical WNT pathway, though the precise molecular mechanism remained unknown." (PMID 38007497, 2023). "Downregulation of the EMX2 gene participates in tumor metastasis and reduced overall survival." (PMID 35127943, 2022). "The EMX1 and EMX2’s potential as tumor suppressor genes has been suggested in some cancers." (PMID 34016958, 2021). "In vitro EMX2 silencing promoted cell proliferation, invasive phenotypes, and activation of the canonical Wnt pathway, suggesting that EMX2 may be a tumor suppressor gene." (PMID 34016958, 2021). "Therefore, the tumor-suppressive effect of the EMX1/EMX2 genes measured in terms of the proliferative rate and clone formation is lost when mutant CTNNB1 is overexpressed." (PMID 34364391, 2021). "In addition, it was found that coexpression of mutant CTNNB1 with EMX1 or EMX2 individually or both EMX genes (EMX1 + EMX2) enabled reversion to a more aggressive tumor phenotype due to increased cell proliferation and clonogenicity." (PMID 34364391, 2021). "Although rarely reported, we speculate that EMX2OS also serves as a tumor suppressor because of its strong co-expression relationship with EMX2." (PMID 33234727, 2020). "Additionally, there was an obviously significant positive correlation between EMX2OS and EMX2 in both normal (r = 0.85; p < 0.001) and tumor samples (r = 0.89; p < 0.001)." (PMID 33234727, 2020). "The tumor suppressor role of EMX2 has been characterized in several types of cancer." (PMID 30576338, 2018). "Up or downregulated Teneurin expression could be an indirect consequence of changes in other cancer-related genes, such as altered expression of EMX2 in some tumor types." (PMID 28472127, 2017). "Conversely, overexpression of EMX2 led to an inhibition of tumor cell migration." (PMID 28830374, 2017). "In vitro knockdown of EMX2 resulted in increased tumor cell migration." (PMID 28830374, 2017). "Finally, Emx2 overexpression driven by the stem-cell-specific “neuro-Nestin promoter” is still able to fully suppress tumor cultures." (PMID 27191499, 2016). "Finally, in two out of two tested lines, the tumor culture collapse was also achieved when Emx2 was driven by a neural stem cell-specific promoter, likely active within tumor-initiating cells." (PMID 27191499, 2016). "In cells that overexpress EMX2, a small amount of cisplatin-induced DNA damage may be sufficient to trigger apoptotic pathways instead of being simply repaired by the tumor cells." (PMID 26132438, 2015).
tumor (continued). "Because EMT is known to enable cancer cells to invade surrounding tissues and generate distant metastases, and has been shown to be associated with poor prognosis and chemo-resistance in different tumor models, it is tempting to speculate that EMX2 is involved in the regulation of EMT in lung SCC." (PMID 26132438, 2015). "Thus silencing EMX2, which causes aberrant Wnt signaling, might negatively impact squamous differentiation in SCC ultimately leading to tumor development, poor prognosis and resistance to therapy." (PMID 26132438, 2015). "Our findings suggest that EMX2 expression is a marker of poor prognosis in ESCC and plays a unique role in regulating tumor stemness and chemotherapeutic sensitivity." (PMID 40564092, 2025). "During tumor progression, CAPZA1, GRB2, NF2EL3, PLEKHO1, SIGLEC1, and UBE2Z were expressed at higher levels in late-stage KIRC, whereas EMX2, FUCA1, IMPA2, and RORC were expressed at higher levels in early-stage KIRC." (PMID 35127943, 2022). "CAPZA1, HLA-E, IMPA2, NFE2L3, PLEKHO1, SIGLEC1, and UBE2Z were expressed at higher levels in tumor tissues, whereas EMX2, FGL2, FUCA1, and GRB2 were expressed at lower levels in tumor tissues." (PMID 35127943, 2022). "Compared with the matched tumor-free samples, EMX2OS and EMX2 expression levels were downregulated in 91.7% (11 of 12) and 83.3% (10 of 12) of KIRC samples, respectively." (PMID 33234727, 2020). "Supporting an EMX2‐HOX switch, tumour regions also showed high levels of multiple HOX genes from all clusters (Fig EV3C)." (PMID 31468686, 2019). "More importantly, re‐expression of EMX2 completely prevented the growth of GBM xenografts in immunocompromised mice, indicating a potent tumour‐suppressive function for EMX2." (PMID 31468686, 2019). "Importantly, repression of EMX2 and upregulation of many HOX genes significantly correlated with tumour grade, indicating the clinical relevance of the aberrant transcriptional patterns observed in patients (EV3D and EV4D)." (PMID 31468686, 2019). "Last but not least, restricting Emx2 overexpression to presumptive tumor stem cells replicated the outcome of generalized gene overexpression." (PMID 27191499, 2016). "This suggests that while EMX2 may not directly regulate the size of the cancer stem-like population, it enhances the functional properties required for tumor initiation and progression." (PMID 40564092, 2025). "Functional proliferation, clone formation, and tumor formation tests and measurement of the expression levels of genes related to stem cell biology were performed to evaluate the effect of the constitutively active Wnt pathway on the individual or combined overexpression of the EMX1/EMX2 genes." (PMID 34364391, 2021). "In tumor cells derived from other tissues, Teneurins and EMX2 were not necessarily coexpressed." (PMID 28472127, 2017). "The results indicated a reduction in the number, size, and efficiency of tumor formation, as well as a negative correlation of the CD133+ fraction with the EMX1 and EMX2 levels." (PMID 34016958, 2021). "Expression data from laser microdissected regions corroborated the anti‐correlation observed across patients, showing opposing EMX2 and EZH2 expression patterns between tumour regions and normal adjacent tissue within individual samples." (PMID 31468686, 2019).
cancer (16 papers, 2012 to 2025). A tumor composed of atypical neoplastic, often pleomorphic cells that invade other tissues. "Dysregulation of EMX2 expression has been implicated in various pathological conditions, including cancer, but the precise molecular mechanisms underlying EMX2 functions in cancer remain incompletely understood." (PMID 40564092, 2025). "Our results are in agreement with reported descriptions of EMX2 as a protein implicated in the progression of some cancers." (PMID 30514244, 2018). "In conclusion, our study provides compelling evidence that EMX2 plays a pivotal role in ESCC progression by enhancing cancer stemness and correlating with poor patient prognosis." (PMID 40564092, 2025). "While the developmental roles of EMX2 are well documented, its functions in pathological conditions, particularly cancer, are not fully understood." (PMID 40564092, 2025). "EDA, SEMA3G, ENPP5, EMX2, and OPCML were favorable factors and had low expression levels in ccRCC tissues, whereas PCDHGC3 was a risk factor and highly expressed in cancer tissues." (PMID 36505496, 2022). "EMX1/EMX2 reduce the activation of the Wnt pathway, properties of cancer stem cells, and expression of genes that regulate stemness." (PMID 34364391, 2021). "To validate the results, we explored the differential expression and prognostic value of EMX2OS and its correlation with EMX2 in pan-cancer data (32 other cancer types) from The Cancer Genome Atlas (TCGA) as an internal validation." (PMID 33234727, 2020). "Kaplan-Meier survival analysis and correlations analysis for EMX2OS and EMX2 in pan-cancer (33 types of cancer from TCGA)." (PMID 33234727, 2020). "Recent studies suggest possible involvement of EMX2 in human cancers; however, the role of EMX2 in carcinogenesis needs further exploration." (PMID 23029345, 2012). "Since the functional differences between sp1 and sp2 isoforms are still unknown, they may be crucial for a unique function of EMX2 in cancer cells." (PMID 40564092, 2025). "We therefore hypothesised that whilst complementary functions of EZH2 and EMX2 ensure controlled self‐renewal of normal cells, cancer cells may benefit from EMX2 silencing to unlock unrestrained proliferation." (PMID 31468686, 2019). "Inhibition of Wnt signaling by EMX2 has been proposed to block the cell cycle in some cancers." (PMID 30514244, 2018). "We also demonstrated that Wnt signaling pathway was dramatically inhibited by EMX2 in vivo and in vitro, providing further evidence that Wnt signaling pathway may mediate the function of EMX2 in cancer as previously proposed." (PMID 23029345, 2012). "Recent studies suggest possible involvement of EMX2 in human cancers." (PMID 23029345, 2012). "Interestingly, our results indicate that EMX2 decreases the proportion of side population (SP) of ESCC cells but may increase cancer stemness within this fraction, as evidenced by the increased colony formation capacity in EMX2-expressing cells." (PMID 40564092, 2025). "We therefore focused on EMX2, which becomes an EZH2 target specifically in cancer cells." (PMID 31468686, 2019). "All ten samples analyzed were found to exhibit either lack of EMX2 expression or decreased levels of EMX2 expression in cancer tissues when compared to their normal counterparts (P<0.01)." (PMID 23029345, 2012). "When the distributions of EMX2 expression levels were visualized, they showed a uniform expression pattern in non-cancerous esophageal epithelial tissues, an all-or-none pattern in cancer cell lines, especially in ESCC cell lines, and a likely mixture of them in ESCC tissues." (PMID 40564092, 2025).
infection (4 papers, 2010 to 2020). The state of being infected such as from the introduction of a foreign agent such as serum, vaccine, antigenic substance or organism. "Nevertheless, our ectopic Emx2 experiments using AAV indicate that tdTomato signal was detectable within 36 hr of AAV-Emx2 infection." (PMID 32965215, 2020). "We likewise examined the significance of EMX2 in cell migration by infection of DLD1 cells (which display low EMX2 expression levels at normal baseline conditions) with an adenovirus expressing EMX2 (Ad-EMX2), or with an empty vector control (Ad-Null)." (PMID 28830374, 2017). "Infection of tumors with Ad-EMX2 significantly suppressed proliferation and more importantly, improved overall survival." (PMID 23029345, 2012). "The growth of AGS and MKN28 cells was significantly suppressed upon infection with adenovirus expressing EMX2 (Ad-EMX2) compared with an empty vector control (Ad-ctrl) (P<0.001), whereas the growth of AZ521 cells was not affected (P>0.05)." (PMID 23029345, 2012). "Compared with lentivirus-C treated controls, relative levels of Emx2-mRNA upon OS1-179(+) infection, changed by a factor of 0.56/1 = 0.56 (p<0.001) - and 1.42/1.65 = 0.87 (p<0.01), in wild type and Dicer1-KD NIH/3T3 cells, respectively." (PMID 20066053, 2010). "To assess if upregulation of Emx2 induced by miR-αEmx2OS-774 took place at transcriptional or post-transcriptional level, we then measured Emx2 pre-mRNA levels, following infection of neurospheres with miR-αEmx2OS-774 or negative control lentiviruses." (PMID 20066053, 2010).
neurodegenerative disease (1 paper, 2023). A disorder of the central nervous system characterized by gradual and progressive loss of neural tissue and neurologic function. "Key genes in brain development and cortical regionalization, such as the Empty Spiracle Homeobox 1 and 2 (EMX1 and EMX2) genes, are abnormally methylated in neurodegenerative diseases." (PMID 36875702, 2023).
EMX2 also shares sentences with these, for which no sentence is quoted: Anxiety (2 papers); cryptorchidism (2); osteosarcoma (2); brain glioma (1); colorectal (1); developmental delays (1); epilepsy (1); Ewing sarcoma (1); head and neck tumors (1); Hypergonadotropic hypogonadism (1); hypospadias (1); intellectual disabilities (1); liposarcoma (1); Micropenis (1); microphthalmia (1); neuroblastoma (1); Obesity (1); Parkinson disease (1); Primary amenorrhea (1); renal hypoplasia (1); synovial sarcoma (1); vesicoureteral reflux (1); Wilms tumor (1).